MLKL (mixed lineage kinase domain like pseudokinase)
Diseases named in the same sentence as MLKL in open-access papers (continued):
Sharing a sentence is not in itself a finding about the gene and the disease.
cardiac hypertrophy (4 papers, 2021 to 2023). "Meanwhile, we demonstrated that overexpression of RIP3 is implicated in the pathogenesis of myocardial hypertrophy by promoting MLKL cell membrane localization, which further increases intracellular calcium influx." (PMID 35464769, 2022). "Overexpression of RIPK3 simultaneously up-regulated the expression of RIPK1 and the phosphorylation of MLKL in the myocardial tissues of mice with cardiac hypertrophy." (PMID 37833985, 2023). "Research has shown that RIP3 interacts with mixed lineage kinase domain-like protein (MLKL) and promotes its cell membrane localization to increase the influx of calcium within cells, thereby mediating the development of myocardial hypertrophy." (PMID 37833985, 2023). "Western blotting analysis showed that the expressions of RIPK1 and phosphorylated MLKL in the myocardium of RIPK3−/− mice with myocardial hypertrophy were significantly lower compared with WT mice." (PMID 37833985, 2023). "Our results showed that the expression of RIPK1 and the phosphorylation of MLKL were significantly up-regulated in the myocardium of WT mice with myocardial hypertrophy, and the levels of serum IL-6 and TNF-α were increased." (PMID 37833985, 2023). "The results of the present study revealed that expression of RIPK1 and phosphorylation of MLKL were significantly upregulated in the myocardium of WT myocardial hypertrophy mice, and the levels of serum IL-6 and TNF-α were increased." (PMID 36046685, 2022). "Of course, during this experiment, we only paid attention to the changes in calcium ions caused by MLKL localization on the cell membrane and did not detect whether the myocardial hypertrophy caused by MLKL was caused by Na+ changes." (PMID 35464769, 2022). "In mice with cardiac hypertrophy, the expression of RIPK3 downstream protein RIPK1 and the phosphorylation of MLKL were inhibited, and meanwhile, apoptosis was improved." (PMID 37833985, 2023). "In mechanism, we demonstrated that RIP3 interacts with mixed lineage kinase domain-like protein (MLKL) and promotes its cell membrane localization to increase the influx of calcium within cells, thereby mediating the development of myocardial hypertrophy." (PMID 35464769, 2022). "In addition, the EAM group in “early” stages (3W) developed severe cardiac dysfunction, including decrease of EF and FS, ventricular dilation, and hypertrophy with reduced RIP1, RIP3, and MLKL expression." (PMID 34497836, 2021).
cardiomyopathy (4 papers, 2017 to 2025). A disease of the heart muscle or myocardium proper. "Firstly, current studies on cardiomyopathy-induced PANoptosis primarily rely on simultaneous detection of apoptosis markers (e.g., cleaved Caspase-3), pyroptosis markers (e.g., GSDMD-N), and necroptosis markers (e.g., p-MLKL) as evidence of PANoptosis activation." (PMID 41479920, 2025).
Hyperglycemia (4 papers, 2020 to 2025). An increased concentration of glucose in the blood. "However, under hyperglycemia, MLKL phosphorylates CB2R to mediate its ubiquitination degradation and promote necroptosis and diabetic heart dysfunction." (PMID 40305291, 2025). "While the exact mechanisms for hyperglycemia-elevated ROS production in mitochondria is yet to be determined, it has been shown that during canonical necroptosis RIP1, RIP3, and MLKL translocate to the mitochondria and stimulate ROS production." (PMID 33298902, 2020).
Listeria infection (4 papers, 2021 to 2024). "For instance, Listeria monocytogenes infection induced activation of RIPK3-MLKL signaling axis in human cells, and the active MLKL directly bound to the bacteria and inhibited the bacterial replication." (PMID 38292869, 2024). "Moreover, Studies have shown that the activation of MLKL induced by Listeria infection does not cause intestinal epithelial cell necroptosis, on the contrary, MLKL can directly bind to Listeria, thereby inhibiting pathogen replication." (PMID 38933265, 2024). "In accordance to the deubiquitinase activity of OTUB1 on K48-linked polyubiquitin chains of c-IAP1, we detected enhanced K48-linked polyubiquitination of c-IAP1 in the livers of OTUB1LPC-KO mice upon Listeria infection, which was independent of MLKL." (PMID 33712742, 2021). "So far it has been exemplified in listeriosis, that infected Kupffer cells undergo RIPK1/MLKL-dependent necroptosis, whereas hepatocytes may become apoptotic [11, 12 and this study]." (PMID 33712742, 2021). "Notably, recent studies have suggested that the phosphorylation of MLKL by itself may be insufficient to prove the activation of necroptosis, as it failed to induce host cell death during Listeria infection." (PMID 35708336, 2022).
lupus (4 papers, 2016 to 2023). "Activation of necroptosis by RIPK3 or MLKL in macrophages is dependent on DNA sensing and is elevated in autoimmune conditions like systemic lupus erythematosus (SLE)." (PMID 38139802, 2023). "In SLE patients, MLKL mRNA was found to be upregulated in patients with lupus nephritis (LN) as compared with patients without LN, and also higher in active patients than in stable patients." (PMID 33054864, 2020). "Mixed lineage kinase domain-like pseudokinase (MLKL) has been identified as a key executor of necroptosis; however, the significance of MLKL in peripheral blood mononuclear cells (PBMCs) of systemic lupus erythematosus (SLE) has not been investigated." (PMID 33054864, 2020).
maturity-onset diabetes (4 papers, 2021 to 2023). "A rare missense loss-of-function mutation in MLKL was also found to exclusively segregate with the affected male and female siblings suffering from maturity-onset diabetes of the young (MODY)." (PMID 36755069, 2023). "These include MLKL in endosomal trafficking, insulin sensitivity, and type II diabetes or the requirement for MLKL for myelin sheath breakdown." (PMID 34079078, 2021).
pancreatic ductal adenocarcinoma (4 papers, 2015 to 2024). An infiltrating adenocarcinoma that arises from the epithelial cells of the pancreas. "On the other hand, RIPK1/3- and MLKL-dependent necroptosis in pancreatic ductal adenocarcinoma (PDA) cells would recruit and activate immunosuppressive TAMs and myeloid cells." (PMID 35422482, 2022). "In pancreatic ductal adenocarcinoma (PDAC), RNA sequencing and multiplex immunofluorescence have shown that early-stage liver metastatic patients (T1M1) exhibit increased expression of mixed lineage kinase domain-like pseudokinase (MLKL)." (PMID 39676861, 2024).
pancreatitis (4 papers, 2017 to 2022). Inflammation of the pancreas. "Twelve-week-old Atg7Δpan mice showed increased activation of trypsin, RIP3, and MLKL at baseline, but more so in response to LPS, suggesting that the depletion of Atg7 from acinar cells is sufficient to predispose the tissue to pancreatitis." (PMID 33087696, 2020). "However, in another caerulein-induced-pancreatitis study using RIPK3- or MLKL-deficient mice, compared with the control group, the pancreatic edema and inflammation in RIPK3−/− and MLKL−/− mice were more severe, and more inflammatory cells were recruited into the pancreas." (PMID 35740953, 2022).
Thrombocytopenia (4 papers, 2015 to 2025). A reduction in the number of circulating thrombocytes. "However, a constitutively active MLKL variant (D139V mutation) significantly reduces platelet counts in knock-in mice, indicating that aberrant MLKL hyperactivation can induce thrombocytopenia, likely through necroptosis which is triggered by RIPK3 or other signaling mechanisms." (PMID 40710328, 2025). "Patients with severe thrombocytopenia displayed significantly higher expression levels of MLKL and Beclin-1 than those who had moderate thrombocytopenia (4.03 ± 0.63 and 4.73 ± 0.56 vs 1.54 ± 0.22 and 1.99 ± 0.33, respectively)." (PMID 35699825, 2023). "Furthermore, the degree of thrombocytopenia was positively correlated with both MLKL and Beclin-1 expression levels." (PMID 35699825, 2023). "Analyses at steady state and post antibody-mediated thrombocytopenia revealed that platelet production was normal in the absence of MLKL, however low dose thrombin-mediated platelet activation and haemostasis were impaired." (PMID 33510145, 2021). "Analyses at steady state and post antibody-mediated thrombocytopenia revealed that platelet production was normal in the absence of MLKL, however, platelet activation and haemostasis were impaired." (PMID 33510145, 2021). "Analyses at steady state and post antibody-mediated thrombocytopenia revealed that platelet production was normal in the absence of MLKL, however, platelet activation and haemostasis were impaired with prolonged tail re-bleeding times." (PMID 33510145, 2021).
thrombosis (4 papers, 2018 to 2022). "The KEGG enrichment analyses indicated that the highly expressed IL-17B in the vascular wall during thrombosis was significantly associated with the RIP3/MLKL signaling pathway." (PMID 36046722, 2022). "Taken together, Mlkl deficiency reduces clot size in IVC thrombosis, possibly by abrogating MLKL-dependent necroptosis of blood cells, especially neutrophils." (PMID 30062055, 2018). "This triggers mixed lineage kinase-like (MLKL) phosphorylation and its activation, which in turn contributes to venous thrombosis by driving NET release from the neutrophils." (PMID 36430952, 2022). "Those that have been performed, however, suggest an important role of the RIPK1/RIPK3/MLKL driven necroptosis pathway in venous thrombosis." (PMID 33142926, 2020). "Given the ready availability of inhibitors of RIPK1/RIPK3 and the large clinical impact of venous thrombosis annually worldwide, the mechanistic relationship between RIPK1/RIPK3/MLKL, platelets, NETosis and venous thrombosis certainly merits further investigation." (PMID 33142926, 2020). "Thrombosis was significantly reduced in RIP3-/- and MLKL-/- mice compared with WT mice (all P < 0.001)." (PMID 36046722, 2022). "Therefore, the aim of this study was to examine the effects of RIP3, MLKL, and IL-17B on cell viability in vitro and to examine the role of IL-17B in regulating RIP3 and MLKL in the vascular wall, thus modulating thrombosis, in a DVT mouse model." (PMID 36046722, 2022).
acute respiratory distress syndrome (3 papers, 2021 to 2023). Progressive and life-threatening pulmonary distress in the absence of an underlying pulmonary condition, usually following major trauma or surgery. "As the co-chaperone of HSP90, PTGES3 (P23) has been found can activate the RIPK3/MLKL during the necroptosis in acute respiratory distress syndrome." (PMID 38020922, 2023).
aneurysm (3 papers, 2019 to 2025). Bulging or ballooning in an area of an artery secondary to arterial wall weakening. "Phospho-MLKL was nearly undetectable in sham controls, but became prominent in aortic tissues subjected to aneurysm induction, almost exclusively in medial SMCs." (PMID 34572045, 2021). "The aneurysm prone aortic tissues of the DMSO-treated mice contained PI-positive necrotic cells, elevated levels of phospho-MLKL, as well as terminal deoxynucleotidyl transferase dUTP nick end labeling (TUNEL)-positive apoptotic cells and CD68-positive macrophages." (PMID 30842407, 2019).
bladder cancer (3 papers, 2015 to 2022). "The abilities of NSA and Mdivi-1 to significantly rescue T24 cells from 3-BrPA render MLKL and Drp1 major determinants of drug’s cytotoxicity in bladder carcinoma." (PMID 26198749, 2015). "Furthermore, scabertopin can mediate necroptosis of bladder cancer cells by activating the RIP1/RIP3/MLKL pathway through phosphorylation and inhibit the proliferation and viability of bladder cancer cells." (PMID 36497458, 2022). "To further test whether compound 13i HCl increases necroptosis in bladder cancer cells, we evaluated the marker of necroptosis, phosphorylated MLKL (pMLKL) by western blotting." (PMID 32282334, 2020). "After its MCT1- and NHE1-directed entry in oncogenic H-Ras-transformed bladder cancer cells, 3-BrPA activates the PARP and RIPK3/MLKL/Drp1 necrotic axes, presumably together with the RIPK3/MLKL/TRPM7, RIPK3/MLKL/NHE1 and RIPK3/SAPK/JNK necrotic subroutines, in RIPK1-independent manner." (PMID 26198749, 2015).
breast tumor (3 papers, 2020 to 2025). "It was proposed that MLKL drives secretion of the pro-survival cytokines by breast tumor cells and that these cytokines induce cellular paracrine survival signals." (PMID 39979285, 2025). "For instance, while in breast tumors, high MLKL expression associated with poor prognosis, yet in CRC low MLKL expression predicted shorter overall survival in the patients." (PMID 32752206, 2020). "MLKL inactivation was also shown to block lysosomal degradation of the death receptor DR5 in lung and breast tumor cells and thereby enhance cell death upon treatment with TRAIL, the DR5 ligand." (PMID 39979285, 2025). "Another study regarding mouse MMVT-PyMT breast tumor showed that RIPK3 expression was decreased in the early stages, but a significant increase of RIPK3 and MLKL expression was detected in late stage tumors that bear tumor necrosis, suggesting the necroptosis promotes tumor development 17,18." (PMID 32742497, 2020).
colorectal adenocarcinoma (3 papers, 2022 to 2023). The most common type of colorectal carcinoma. "Mechanically, this phosphorylation was found to improve MLKL association with the endosomes and promote endosomal trafficking, resulting in enhanced release of EVs containing ph-MLKL in the colorectal adenocarcinoma cells." (PMID 36435789, 2022). "Another study showed that activated MLKL promotes PS exposure on interferon (IFN)-ɣ induced necroptotic mouse embryonic fibroblast cells and human colorectal adenocarcinoma cells, supporting the PS exposure-promoting role of MLKL in necroptotic cells." (PMID 37091984, 2023).
glaucoma (3 papers, 2022 to 2025). Increased pressure in the eyeball due to obstruction of the outflow of aqueous humor. "Moreover, GSK872 and Nec-1 can protect RGCs from necroptosis and suppress NLRP3 inflammasome activation through inhibition of RIP1/RIP3/MLKL pathway, conferring a novel neuroprotective treatment for glaucoma." (PMID 36289519, 2022). "In addition, the involvement of necroptosis in ONC and IRI glaucoma models was examined by utilizing RIP1 kinase-dead (RIP1-KD), RIP3 knockout (RIP3-KO), and MLKL knockout (MLKL-KO) mice." (PMID 39448868, 2025). "In the NMDA-induced excitotoxic glaucoma model, microglia were activated and the release of TNFα from activated microglia may spread around RGCs and activate the TNFR1 of RGCs, leading to RIP1/RIP3/MLKL pathway activation and following RGCs necroptosis." (PMID 36289519, 2022). "Thus, we could infer that the RIP1/RIP3/MLKL pathway contributes to glutamate-induced NLRP3 inflammasome activation, and it may be one of the upstream regulators of NLRP3 inflammasome activation in glaucoma." (PMID 36289519, 2022). "In this study, a comprehensive evaluation of two experimental glaucoma models, ONC and IRI, was conducted in mice lacking core proteins in the necroptosis pathway (RIP3-KO and MLKL-KO) or expressing a kinase-dead form of RIP1 (RIP1-KD)." (PMID 39448868, 2025).
gout (3 papers, 2017 to 2018). A condition characterized by painful swelling of the joints, which is caused by deposition of urate crystals. "Targeting RIP1 and MLKL was shown to suppress MSU-induced cell death in vitro while MLKL-deficient mice lacked tophus formation in a gouty arthritis model, providing further confirmation of the involvement of the RIP1-RIP3-MLKL axis." (PMID 29892292, 2018).
idiopathic pulmonary fibrosis (3 papers, 2023 to 2025). Idiopathic pulmonary fibrosis (IPF) is a nonneoplastic pulmonary disease that is characterized by the formation of scar tissue within the lungs in the absence of any known cause. "We detected that the expression of p-MLKL and four other prognostic related genes was significantly increased in fibrotic lung tissue, which laid a foundation for further exploration of the relationship between necroptosis and pulmonary fibrosis." (PMID 37051233, 2023). "Finally, evidence also points to a role for MLKL in Coronary Obstructive Pulmonary Disease (COPD) and Idiopathic Pulmonary Fibrosis (IPF), as active MLKL is elevated in the lung tissues of the patroness of these diseases." (PMID 37373257, 2023). "However, due to the strict setting of our logFC cutoff value, Therefore, RIPK3 and MLKL were not included into the DEGs in the previous analysis of pulmonary fibrosis tissue in GSE110147, so we conducted a follow-up animal experiment for additional verification." (PMID 37051233, 2023).
infarction (3 papers, 2021 to 2023). A localised pathological necrosis of tissue resulting from obstruction of the blood supply usually by a thrombus, an embolus, or vascular torsion. "This innovative study at animal models, cellular, and molecular levels is anticipated to clarify the roles of MLKL and Cx43 in thalamic damage after focal cortical infarction." (PMID 37904209, 2023).
lymphoma (3 papers, 2018 to 2022). A malignant (clonal) proliferation of B- lymphocytes or T- lymphocytes which involves the lymph nodes, bone marrow and/or extranodal sites. "Another pan-kinase inhibitor, staurosporine, a widely used apoptosis inducer, was found to promote RIP3/MLKL-dependent necroptosis in U-937 lymphoma cells under caspase-compromised conditions." (PMID 30583560, 2018). "MLKL-mRNA treatment protected in two syngeneic mouse tumor models and even in mice with a humanized immune system that had been inoculated with human lymphoma cells." (PMID 30143632, 2018). "Moreover, MLKL-mRNA treatment blunts the growth of human lymphoma in mice with a reconstituted human adaptive immune system." (PMID 30143632, 2018). "To address the question whether an intratumor MLKL-mRNA treatment method holds promise for clinical application, we performed experiments in mice with a grafted human immune system that were subsequently inoculated with HLA-matched human lymphoma-derived cancer cells." (PMID 30143632, 2018).
myeloid leukemia (3 papers, 2021 to 2023). A clonal proliferation of myeloid cells and their precursors in the bone marrow, peripheral blood, and spleen. "MLKL was also detectable in human liver cell line (HepG2), human myeloid leukemia mononuclear cell line (Thp-1), and human hepatic stellate cell line (LX2)." (PMID 35836819, 2022). "As RIPK3 functions as a powerful tumor suppressor in myeloid leukemia, we set out to investigate the contribution of its downstream partner MLKL to leukemogenesis." (PMID 34079078, 2021).
myeloma (3 papers, 2022 to 2025). "Our study showed that the anti-myeloma agents induce not only nuclear translocation of total MLKL but also of the C-terminal fragment in MM cells, suggesting that the NLS motif in the C-terminal fragment was exposed after cleavage." (PMID 35965541, 2022). "Furthermore, since these anti-myeloma agents exhibited potent anticancer effects against MM cells from patients, it is reasonable to assume that caspase-mediated MLKL cleavage also occurs in primary MM cells undergoing necroptotic cell death." (PMID 35965541, 2022). "Inhibiting necrosome complex constituents RIPK1/3 did not protect against Ad[CE1A]-induced death, but inhibiting MLKL, the final mediator of necroptosis, significantly protected myeloma cells." (PMID 40247106, 2025). "Despite of the well-documented phosphorylation of MLKL, cleavage of MLKL at Asp140 in the 137-DQQD-140 (D:Asp, Q:Gln) by cysteine-aspartic specific proteases (CASP) -3/8/10 is also found to induce necroptosis in a RIPK3-independent manner from human myeloma (MM) cells." (PMID 40085533, 2025).
Nephropathy (3 papers, 2017 to 2023). A nonspecific term referring to disease or damage of the kidneys. "Previous studies have described that regulated necrosis pathways are activated during FA-AKI and are associated with the upregulation of components in this cell death pathway, such as RIPK3 and MLKL, contributing to cell death and kidney damage." (PMID 37627536, 2023).